DRG2 (developmentally regulated GTP binding protein 2)
Diseases named in the same sentence as DRG2 in open-access papers:
DRG2 is named in the same sentence as 26 diseases in open-access papers, as found by Europe PMC text mining. Sharing a sentence is not in itself a finding about the gene and the disease. The quoted sentences say what the papers report.
astrocytoma (4 papers, 2021 to 2025). "DRG2 was reported to be significantly under expressed in IDH1-mutant astrocytoma, which are frequently ATRX-mutant/ALT-positive." (PMID 39921567, 2025). "In general, the expression of those genes was downregulated in oligodendroglioma when comparing with either astrocytoma or GBM, while the expression of DRG2 is upregulated in both oligodendroglioma and GBM when comparing with astrocytoma." (PMID 38812741, 2024). "Nonetheless, it is still possible to highlight some few exceptional features that were selected DRG2, KCND2, and C14orf23, which allow for the separation of astrocytoma." (PMID 38812741, 2024). "Validation of 6 biomarkers with the highest importance score in TCGA and CGGA cohorts revealed that HS3ST1, and CNN3 were overexpressed in astrocytoma, while SLAIN1, ABTB2, TRIM67 and DRG2 were overexpressed in oligodendroglioma." (PMID 35287567, 2022). "Our analysis of mRNA expression levels showed that two genes that promote cell proliferation and invasion, DRG2 and MSN, were under-expressed in IDH1-mutant astrocytoma compared to normal tissue and IDH1-wildtype patients." (PMID 34503108, 2021). "Most of the selected genes were differentially expressed between GBM and oligodendroglioma but not between GBM and astrocytoma, with the exception of the gene DRG2, where the opposite was verified." (PMID 38812741, 2024).
lung carcinoma (4 papers, 2016 to 2023). "In lung cancer cells, miR-1915 is suggested as an antiapoptotic non-coding RNA by targeting DRG2/PBX2." (PMID 34680382, 2021). "However, downregulation of DRG2 could prevent the apoptosis of lung cancer cells." (PMID 27626498, 2016). "In addition, miR-1915-3p could impair etoposide-induced apoptosis, thereby increasing chemoresistance via downregulating DRG2 and PBX2 in lung cancer cell lines (NCI-H441 and NCI-H1650)." (PMID 34774019, 2021).
melanoma (4 papers, 2021 to 2025). A malignant, usually aggressive tumor composed of atypical, neoplastic melanocytes. "Previously, we reported that expression of DRG2 is significantly higher in human metastatic melanoma than primary melanoma and dysplastic nevi and that DRG2 depletion in melanoma cells inhibits melanoma growth and metastasis in mice." (PMID 38802348, 2024). "We next assessed the potential relevance of DRG2 expression in clinical response of melanoma patients to anti-PD-1 therapy using the Hugo cohort and the Harel cohort." (PMID 38802348, 2024). "We next investigated the effect of DRG2 depletion on the expression of immune-checkpoint molecules in melanoma tumors." (PMID 38802348, 2024). "We also found that DRG2 depletion significantly increased the localization of PD-L1 on Rab5 endosome but decreased it on Rab11 endosomes in SK-MEL-28 human melanoma cells." (PMID 38802348, 2024). "The PD-L1 of DRG2-depleted SK-MEL-28 human melanoma cells also showed reduced colocalization with Con A." (PMID 38802348, 2024). "Cohort analysis revealed that patients bearing melanoma with low DRG2 protein levels were resistant to anti-PD-1 therapy." (PMID 38802348, 2024). "In addition, from data analysis of a melanoma patient cohort under anti-PD-1 treatment, we found that low DRG2 protein expression correlated with a poor clinical response of melanoma patients to anti-PD-1 therapy." (PMID 38802348, 2024). "Here, we analyzed whether DRG2 depletion in melanoma cells affects components of the TIICs, leading to inhibition of tumor growth." (PMID 38802348, 2024). "Furthermore, depletion of DRG2 reduces the proliferation and soft agar colony formation of melanoma cells whilst also reducing tumor growth and metastasis in mice." (PMID 34664086, 2021). "However, high DRG2 expression was correlated with a lower survival rate in melanoma patients." (PMID 39996178, 2025). "Additionally, mice bearing DRG2-depleted melanoma did not respond to anti-PD-1 treatment, and data analysis of a melanoma patient cohort undergoing anti-PD-1 treatment revealed that low DRG2 protein expression correlated with poor clinical response in melanoma patients." (PMID 39857640, 2024). "We also found that DRG2 depletion significantly increased the expression of PD-L1 and IRF1 in SK-MEL-28 human melanoma cells and CT26 murine colorectal carcinoma cells." (PMID 38802348, 2024). "Here, we have shown that even though DRG2-depleted cancer cells express high level of PD-L1, mice bearing DRG2-depleted melanoma did not respond to anti-PD-1 treatment." (PMID 38802348, 2024). "DRG2 depletion enhanced IFN-γ signaling and increased the PD-L1 level in melanoma cells." (PMID 38802348, 2024). "However, DRG2 RNA levels did not correlate with clinical response in a cohort of melanoma patients treated with anti-PD-L1 therapy." (PMID 39857640, 2024).
glioma (3 papers, 2024 to 2025). A benign or malignant brain and spinal cord tumor that arises from glial cells (astrocytes, oligodendrocytes, ependymal cells). "DRG2 was previously shown to be downregulated in IDH1-mutant gliomas, where ATRX mutations are common." (PMID 40775769, 2025). "Similarly, we examined patterns of gene dysregulation in glioma tumour samples and found that downregulation of DRG2 was strongly associated with ATRX-loss in LGG." (PMID 39921567, 2025). "Here, we have identified loss of SETD2, dysregulation of redox genes such as DRG2 and exposure to hypoxia as sources of excessive ROS in ALT-positive gliomas." (PMID 39921567, 2025). "For instance, DRG2 emerged as the top contributor in classification of ATRX alterations in lower-grade gliomas and was significantly downregulated in ATRX mutant tumours." (PMID 40775769, 2025). "In particular, we have defined two novel sources of ROS in gliomas: co-mutation of SETD2 in HGG and downregulation of DRG2 in LGG." (PMID 39921567, 2025). "We identified three sources of elevated ROS in ALT-positive gliomas: co-mutation of SETD2, downregulation of DRG2, and hypoxic tumour microenvironment." (PMID 39921567, 2025). "ATRX showed one of the strongest transcriptional signatures in lower-grade gliomas (LGG), with the DRG2 gene emerging as the top feature in classification." (PMID 40775769, 2025). "One of the DEGs, developmentally regulated GTP-binding protein 2 (DRG2), was a particularly striking outlier, and was consistently downregulated in ATRX-mutant low grade glioma." (PMID 39921567, 2025).
Anxiety (1 paper, 2019). Intense feelings of nervousness, tension, or panic often arise in response to interpersonal stresses. "The alterations in motor coordination and anxiety behaviors in DRG2−/− mice prompted us to test whether DRG2 depletion causes defects in dopamine neurons." (PMID 31861806, 2019). "The data showed that both male and female 12-week-old DRG2−/− mice spent significantly less time in the open arms than WT mice of the same age, suggesting that DRG2 depletion increased anxiety-like behavior in mice." (PMID 31861806, 2019). "DRG2 knockout (KO) mice displayed defects in motor function in motor coordination and rotarod tests and increased anxiety." (PMID 31861806, 2019). "Collectively, our results suggest that DRG2 depletion reduces the release of nigrostriatal dopamine, which leads to altered motor coordination and anxiety behaviors." (PMID 31861806, 2019).
breast carcinoma (1 paper, 2024). "However, previous studies have reported that DRG2 regulates the endosomal trafficking of surface receptors, such as the transferrin receptor and epidermal growth factor receptor, in breast cancer and cervical cancer cells." (PMID 39857640, 2024).
endothelial dysfunction (1 paper, 2022). In vascular diseases, endothelial dysfunction is a systemic pathological state of the endothelium (the inner lining of blood vessels) and can be broadly defined as an imbalance between vasodilating and vasoconstricting substances produced by (or acting on) the endothelium. "Together, these results suggest that DRG2 deficiency leads to endothelial dysfunction and impaired angiogenesis through upregulation of ROS and senescence in endothelial cells." (PMID 35270019, 2022). "In summary, we demonstrated that DRG2 deficiency can induce endothelial dysfunction, such as reduced blood flow and a decrease in angiogenesis in vivo, ex vivo, and in vitro." (PMID 35270019, 2022). "Even though we did not determine whether there was an enhanced frequency of vascular diseases in DRG2−/− mice, DRG2 deficiency can increase ROS and, thus, endothelial dysfunction and lead to vascular diseases." (PMID 35270019, 2022).
hepatocellular carcinoma (1 paper, 2016). A malignant tumor that arises from hepatocytes. "As a homologous, DRG2 was also reported as a chemotherapeutic drugs resistance marker in hepatocellular carcinoma cells." (PMID 27626498, 2016).
lung adenocarcinoma (1 paper, 2022). A carcinoma that arises from the lung and is characterized by the presence of malignant glandular epithelial cells. "In this study, we trained and validated 16 DDR genes with prognostic values and classification effects in early-stage lung adenocarcinoma and classified patients into two subtypes, DRG1 and DRG2." (PMID 35813819, 2022).
non-small cell lung carcinoma (1 paper, 2023). A group of at least three distinct histological types of lung cancer, including non-small cell squamous cell carcinoma, adenocarcinoma, and large cell carcinoma. "Overexpression of EREG, GTPBP2, and DRG2 was linked to tumor growth in non-small cell lung cancer." (PMID 36809921, 2023).
osteosarcoma (1 paper, 2025). A usually aggressive malignant bone-forming mesenchymal neoplasm, predominantly affecting adolescents and young adults. "Further, ATRX loss was significantly associated with DRG2 downregulation in several other tumour types which are frequently ALT-positive, such as HGG, osteosarcoma, paraganglioma, and phaeochromocytoma." (PMID 39921567, 2025).
ovarian carcinoma (1 paper, 2024). A malignant neoplasm originating from the surface ovarian epithelium. "We selected 2 groups of human tumors: group 1 (thymoma) with higher DRG2 expression in tumors than paired normal tissues and group 2 (ovarian carcinoma) with lower DRG2 expression in tumors than paired normal tissues." (PMID 38802348, 2024).
cancer (10 papers, 2022 to 2025). A tumor composed of atypical neoplastic, often pleomorphic cells that invade other tissues. "Previously, we reported that DRG2 deficiency induces mitochondrial dysfunction and increases intracellular ROS in cancer cells." (PMID 35270019, 2022). "Taken together, these findings implied a potential causal role for DRG2 loss in ALT-cancers." (PMID 39921567, 2025). "We reported previously that DRG2 deficiency increases intracellular ROS levels in cancer cells." (PMID 35270019, 2022). "DRG2-depleted cancer cells exhibit defects in the trafficking of PD-L1 from early endosomes to recycling endosomes and lysosomes, resulting in PD-L1 accumulation in early endosomes rather than on the cell surface." (PMID 39857640, 2024). "The next question was how DRG2 depletion in cancer cells inhibits the efficacy of anti-PD-1 antibody in reinvigorating effector-like T cells." (PMID 38802348, 2024). "In this study, we found that DRG2 depletion delayed the trafficking of PD-L1 from Rab5 early endosome to Rab11 recycling endosome in cancer cells, which led to a decrease in the surface membrane PD-L1." (PMID 38802348, 2024). "Overall, our results suggest that DRG2 modulates anti-PD-1 therapy through regulation of endosomal trafficking of PD-L1 in cancer cells." (PMID 38802348, 2024). "Our results suggest that even though DRG2 depletion enhanced the PD-L1 level in cancer cells, it inhibits the endosomal trafficking of PD-L1 and decreases the PD-L1 level on the surface of cancer cells, which results in poor response to anti-PD-1 therapy." (PMID 38802348, 2024). "They discovered that DRG2 is a critical regulator of PD-L1 endosomal trafficking in cancer cells, which is essential for the proper localization of PD-L1 on the cell surface." (PMID 39857640, 2024). "The endosomal accumulation of PD-L1 in DRG2-depleted cancer cells limited the response of mice bearing the DRG2-depleted tumor to anti-PD-1 therapy." (PMID 38802348, 2024). "Conversely, cancer cells with high DRG2 expression display proper localization of PD-L1 on the cell surface, thereby facilitating a more effective response to ICIs." (PMID 39857640, 2024). "Here, we demonstrate that DRG2 is a key regulator of endosomal trafficking of PD-L1 in cancer cells, and DRG2 depletion inhibits the recycling of PD-L1, resulting in accumulation of PD-L1 in endosomes." (PMID 38802348, 2024). "Considering the continuous internalization and recycling of PD-L1 within endosomes, it is possible that DRG2 depletion in cancer cells may block the recycling of internalized PD-L1 and thus reduce the portion of cell surface PD-L1." (PMID 38802348, 2024). "We next determined whether DRG2 depletion in cancer cells affects the expression of genes involved in the T-cell immune checkpoint." (PMID 38802348, 2024). "We thus determined whether DRG2-depleted cancer cells with enhanced PD-L1 expression have defects in suppressing T cell activity by co-culturing mouse splenic CD4+ T cells with IFN-γ-stimulated B16F10 cells." (PMID 38802348, 2024). "Here, we demonstrate that DRG2 depletion increased expression of PD-L1 in cancer cells but it altered intracellular trafficking of PD-L1 and led to endosomal localization of PD-L1 in cancer cells." (PMID 38802348, 2024). "We confirmed the DRG2 depletion in B16F10/shDRG2 cancer cells." (PMID 38802348, 2024). "We previously demonstrated that DRG2 depletion in cancer cells suppresses tumor angiogenesis." (PMID 35270019, 2022). "Our previous data suggested that DRG2 in cancer cells is involved in tumor angiogenesis." (PMID 35270019, 2022). "Recently, it was shown that DRG2 knockdown induces Golgi fragmentation and mitochondrial dysfunction, decreases the stability of Rac1-positive membrane tubules in cancer cells, and suppresses VEGF-A production in melanoma cells, leading to inhibition of tumor angiogenesis." (PMID 35270019, 2022). "It remains unclear whether DRG2 plays a similar role in other cancer types." (PMID 39857640, 2024).
cancer (continued). "However, it remains unclear whether these mechanisms are the primary regulators of DRG2 in cancer cells." (PMID 39857640, 2024). "The strategic inhibition of multiple factors—DRG2, TRAPPC4, HIP1R, and CMTM6—represents a compelling approach to regulate PD-L1 surface levels on cancer cells, potentially reversing immune resistance mechanisms and amplifying the effectiveness of PD-1/PD-L1 blockade strategies." (PMID 40507229, 2025). "This complex interplay emphasizes DRG2’s critical importance in cancer pathophysiology, functioning not just in receptor transport but comprehensively in tumor immune evasion processes." (PMID 40507229, 2025). "Unlike CMTM6, DRG2 depletion prolonged the localization of PD-L1 at Rab5 early endosomes and increased the total PD-L1 level in cancer cells." (PMID 38802348, 2024). "Even though anti-PD-1 treatment decreased the percentage of cancer cells in subcluster “Autophagy” in DRG2-depleted tumors, this did not lead to inhibition of the tumor progression, possibly because of expansion of the subcluster “Spp1 + ” population." (PMID 38802348, 2024). "GEPIA2 database analysis of 33 cancer types showed the following top 10 ALKBH5-related genes: GID4 (R=0.71), TOP3A (R=0.67), MAPK7 (R=0.66), NT5M (R=0.61), FLII (R=0.59), ZNF18 (R=0.57), DRG2 (R=0.57), COPS3 (R=0.56), MED9 (R=0.56) and PRPSAP2 (R=0.56) (all P<0.0001)." (PMID 35444654, 2022). "Further analysis demonstrated that DRG2 positively correlated with multiple steps in anti-tumor immune response, including recruitment of CD8+ T cell, NK cell, Th1 cell, and Th 17 cell, as well as recognition and killing of cancer cells." (PMID 36159780, 2022). "We also identified the top 1 GEAR in individual cancer types, such as TLL1 (BLCA), PGK1 (BRCA), RFXANK (CESC), DPP7 (COAD), VWA8 (KIRC), SCMH1 (LGG), HILPDA (LIHC), TLE1 (LUAD), CD151 (LUSC), ANKRD13A (OV), SOCS2 (PAAD), DRG2 (PRAD), ADAMTS6 (STAD), PSMB8 (THCA), ASS1 (UCEC)." (PMID 41404730, 2025). "In contrast, even though we did not determine the detailed mechanism, DRG2 depletion enhanced STAT1/IRF1 signaling pathway and the expression of PD-L1 in cancer cells after IFN-γ treatment." (PMID 38802348, 2024).
tumor (10 papers, 2022 to 2025). "We demonstrated a striking correlation between loss of the ATRX gene and downregulation of DRG2 expression in tumour types which are frequently ALT-positive, including LGG and HGG." (PMID 39921567, 2025). "ATRX showed one of the strongest tumour-type-specific transcriptional patterns in LGG tumours, with DRG2 gene having the highest Gini score." (PMID 40775769, 2025). "As expected from our earlier observations, DRG2 depletion impaired the anti-tumor effect of anti-PD-1 antibody." (PMID 38802348, 2024). "To evaluate our findings in a clinical database, we analyzed the expression profile of DRG2 in human tumor samples and paired normal tissues using the Gene Expression Profiling Interactive Analysis (GEPIA) database and its online analysis tool." (PMID 38802348, 2024). "Even though additional cohorts are necessary to validate these findings, the current data suggest a potential correlation between DRG2 protein levels and tumor response to anti-PD-1 therapy." (PMID 38802348, 2024). "Targeting DRG2 could enhance the effectiveness of these therapies by ensuring that PD-L1 is correctly trafficked and exposed to the tumor cell surface, where it can be effectively targeted." (PMID 40507229, 2025). "Third, while tumor cell population in the most dominant cluster (cluster Spp1 + ) decreased after anti-PD-1 treatment in wild-type tumors, the same population expanded in DRG2-depleted tumors after anti-PD-1 treatment." (PMID 38802348, 2024). "The intricate regulatory roles of DRG2, TRAPPC4, HIP1R, and CMTM6 in PD-L1 trafficking and stability present compelling opportunities for therapeutic intervention to enhance anti-tumor immunity." (PMID 40507229, 2025). "How do DRG2-depleted tumor cells escape anti-PD-1 antibody-mediated inhibition without inducing well-known transcriptional programs which contribute to ICB resistance?" (PMID 38802348, 2024). "Anti-PD-1 did not expand effector-like T cells within DRG2-depleted tumors and failed to improve the survival of DRG2-depleted tumor-bearing mice." (PMID 38802348, 2024). "However, our study revealed that DRG2-depleted tumor cells neither induced expression of genes involved in EMT nor suppressed the expression of PD-L1 and MHCs both before and after IFN-γ treatment." (PMID 38802348, 2024). "In addition, single-cell RNA-seq analysis of tumor cells within B16F10 tumors revealed that DRG2 depletion did not generate a specific cluster of tumor cells expressing transcriptional programs involved in the resistance to PD-1 blockade." (PMID 38802348, 2024).
neurodegenerative disease (1 paper, 2019). A disorder of the central nervous system characterized by gradual and progressive loss of neural tissue and neurologic function. "Considering the involvement of Tau and MTs in neurodegenerative diseases, we predict that DRG2 may play an important role in the pathogenesis of neurodegenerative diseases." (PMID 31861806, 2019).
DRG2 also shares sentences with these, for which no sentence is quoted: oligodendroglioma (2 papers); viral infection (2); cervical cancer (1); cocaine addiction (1); colorectal carcinoma (1); dysplastic nevi (1); keratitis (1); metastatic melanoma (1); paraganglioma (1); phaeochromocytoma (1); thymoma (1).